VASH1 (vasohibin 1)
Diseases named in the same sentence as VASH1 in open-access papers (continued):
Sharing a sentence is not in itself a finding about the gene and the disease.
ovarian carcinoma (8 papers, 2014 to 2024). A malignant neoplasm originating from the surface ovarian epithelium. "EZH2 caused VASH1 silencing by promoter methylation and subsequently promoted angiogenesis in ovarian cancer." (PMID 25237831, 2014). "We also found that VASH1 leads to an increase in the proportion of apoptosis and a decrease in ovarian cancer cell proliferation, invasion, and migration ability." (PMID 38281945, 2024). "MEG3 positively regulated the expression level of VASH1 in ovarian cancer cells through hsa-miR-885-5p, exerting an antitumor effect." (PMID 38281945, 2024). "Numerous malignancies, such as upper urinary tract urothelial carcinoma, ovarian carcinoma, squamous cell carcinoma of the esophagus, renal cell carcinoma, and breast carcinoma, exhibit significant VASH1 expression based on several studies." (PMID 39431237, 2024). "Ovarian cancer treatment strategies targeting VASH1 can potentiate the effects of conventional chemotherapy by inhibiting angiogenesis and regulating microtubule activity." (PMID 39710372, 2024). "In conclusion, forced expression of VASH1 in ovarian cancer cells was found to enhance TCP activity, increase cyclin B1 expression, and augment PTX chemosensitivity." (PMID 39710372, 2024). "We demonstrated that MEG3 is influenced by METTL3/YTHDF2 methylation and restrains ovarian cancer proliferation and metastasis by binding miR-885-5p to increase VASH1 expression." (PMID 38281945, 2024). "Western blot analysis of VASH1‐overexpressing ovarian cancer cells revealed upregulated expression of detyrosinated tubulin and cyclin B1 compared with control cells." (PMID 39710372, 2024). "Overexpression of MEG3 suppressed the degradation of VASH1 by negatively regulating miR-885-5p, inhibiting the ovarian cancer malignant phenotype." (PMID 38281945, 2024). "More importantly, this study comprehensively verified the regulatory effect of the MEG3/hsa-miR-885-5p/VASH1 axis on the development of ovarian cancer." (PMID 38281945, 2024). "The forced expression of VASH1 enhanced tubulin carboxypeptidase activity and increased cyclin B1 expression, resulting in augmented paclitaxel chemosensitivity in ovarian cancer cells." (PMID 39710372, 2024). "The outcome of this study implied the antitumor effect of VASH1 in pancancer, confirmed by bioinformatics analysis combining experiments, and provided evidence for new targets to inhibit the progression of ovarian cancer." (PMID 38010374, 2023). "In an effort to further probe the relationship between VASH1 expression and biological significance, the research finally focused on ovarian cancer, exploring drug sensitivity, functional enrichment analysis, and regulation of the malignant phenotype." (PMID 38010374, 2023). "To further explore the specific role of VASH1 in the development of ovarian cancer, we examined the expression of VASH1 in normal ovarian epithelial cells (IOSE80) and ovarian cancer cells (A2780, OVCAR-3, Caov-3, and SKOV3)." (PMID 38010374, 2023). "Overexpression of VASH1 reduces cell proliferation, cloning, and migration in ovarian cancer cell lines." (PMID 38010374, 2023). "VASH1 inhibition of the malignant phenotype of ovarian cancer cells was further confirmed by in vivo experiments." (PMID 38010374, 2023). "In this study, GSEA outcomes also showed that the expression of VASH1 was positively correlated with the ECM receptor interaction pathway in ovarian cancer, including genes related to integrin, collagen, fibronectin, and laminins." (PMID 38010374, 2023). "Next, we explored the antitumor mechanism of VASH1 through drug sensitivity, functional enrichment, and phenotypic experiments in ovarian cancer." (PMID 38010374, 2023). "According to ROC plotter database analysis, patients with high VASH1 expression were more sensitive to multiple first- and second-line chemotherapy drugs for ovarian cancer." (PMID 38010374, 2023).
ovarian carcinoma (continued). "After comprehensively understanding the role of VASH1 across cancers, we focused on its function in ovarian cancer." (PMID 38010374, 2023). "We identified differentially expressed genes correlated with VASH1 in ovarian cancer and concentrated on the potential biological functions of these genes." (PMID 38010374, 2023). "At present, much literature has discussed the clinical role of VASH1 in gastric cancer, ovarian cancer, colorectal cancer, esophageal cancer, prostate cancer, and nonsmall cell lung cancer." (PMID 36504559, 2022). "For example, in cell cultures for ovarian cancer, VASH1 is able to inhibit insulin-like growth factor 1 (IGF-1) expression and inhibit its angiogenesis." (PMID 36504559, 2022). "Paclitaxel, the core chemotherapeutic agent for ovarian cancer chemotherapy, has a point of action on microtubules and may interact with VASH1." (PMID 39710372, 2024). "We previously reported that VASH1 overexpression inhibited tumor growth and peritoneal dissemination by inhibiting tumor angiogenesis, thereby prolonging host survival in murine xenograft models of ovarian cancer." (PMID 39710372, 2024). "In addition, MEG3 has been confirmed to target hsa-miR-885-5p, thereby upregulating the expression of VASH1 and exerting an inhibitory effect on ovarian cancer." (PMID 38281945, 2024). "In this study, we comprehensively demonstrated that lncRNA MEG3 is regulated by METTL3-mediated YTHDF2 methylation; it upregulates VASH1 through regulatory competitive binding to hsa-miR-885-5p and then inhibits ovarian cancer cell proliferation, migration, and invasion." (PMID 38281945, 2024). "We previously reported that subcutaneous or intraperitoneal transplantation of ovarian cancer cells overexpressing VASH1 retarded tumor growth and peritoneal dissemination by inhibiting tumor angiogenesis, thereby prolonging host survival in murine xenograft models." (PMID 39710372, 2024). "Some researchers have reported that VASH1 represents a useful clinical biomarker for metastasis and poor prognosis, and may be a potential therapeutic target in epithelial ovarian cancer." (PMID 39710372, 2024). "In this study, the overexpression of VASH1 increased cyclin B1 expression in ovarian cancer cells." (PMID 39710372, 2024). "In ovarian cancer, VASH1 can serve as a biomarker to estimate the efficacy of chemotherapy." (PMID 38010374, 2023). "This conclusion stems from research on ovarian cancer cells engineered to express a gene for vasohibin-1 (VASH1) that is normally expressed by endothelial cells in response to angiogenic stimuli and inhibits these cells’ motility autocrinally in a negative feedback mechanism." (PMID 28956065, 2018). "Thus, VASH1 may contribute to the comprehensive prevention and treatment of ovarian cancer as a potential therapeutic target." (PMID 38010374, 2023). "Also in ovarian cancer high, VASH-1 expression correlates with other angiogenic factors and Ki-67 expression and may also be a prognostic factor." (PMID 35372578, 2022). "A previous study demonstrated that VASH1 overexpression inhibited tumor growth and angiogenesis in an anti‐VEGF therapy‐resistant, PDGF‐producing ovarian cancer animal model." (PMID 39710372, 2024). "Therefore, in the current study, we examined the influence of VASH1 on intracellular tubulin detyrosination status and PTX chemosensitivity using VASH1‐overexpressing ovarian cancer cell lines." (PMID 39710372, 2024). "Collectively, these results demonstrated that the overexpression of VASH1 increased chemosensitivity to PTX, but not to CDDP, in ovarian cancer cells." (PMID 39710372, 2024). "In contrast, the overexpression of VASH1 did not significantly affect sensitivity to CDDP, another key chemotherapeutic agent for ovarian cancer, possibly because CDDP targets DNA itself, not microtubules." (PMID 39710372, 2024). "Furthermore, VASH1 overexpression significantly augmented sensitivity to PTX, but not to CDDP, in ovarian cancer cell lines." (PMID 39710372, 2024).
colon cancer (6 papers, 2015 to 2024). "Furthermore, Cox proportional risk regression models showed that VASH1 and lymph node metastasis were independent risk factors affecting the prognosis of colon cancer patients, respectively." (PMID 36504559, 2022). "To further confirm the functional role of VASH1 in regulating colon cancer cell growth, we also utilized the loss-of-function strategy to knockdown VASH1 gene with shRNA in VASH1 highly expressed HCT116 tumor cells and then determined its effect on tumor growth and proliferation." (PMID 25797264, 2015). "Notably, our retrospective analysis results showed that VASH1 expression levels in colon cancer cells were solely positively associated with the distant metastases, which is opposite to the results obtained from our in vitro and in vivo studies." (PMID 25797264, 2015). "Given that high density of VASH1 expression in blood endothelial cells in cancer stroma, and that active angiogenesis and lymphoangiogenesis were observed in colon cancer tissues, we next determined whether cancer stroma VASH1 is associated with colon cancer lymphangiogenesis and angiogenesis." (PMID 25797264, 2015). "In colon cancer cells, the expression of circASS1 and VASH1 is reduced, and the high expression of circASS1 can down-regulate miR-1269a, thereby up-regulating VASH1 to inhibit the growth and metastasis of colon cancer." (PMID 35252180, 2022). "We first performed immunohistochemical staining to detect VASH1 expression in 75 colon cancer tissues and 59 paracancerous normal tissues from cancer patients." (PMID 25797264, 2015). "Here we showed that stromal VASH1 levels were negatively correlated with tumor size, advanced clinical stage and distant metastases in colon cancer patients." (PMID 25797264, 2015). "Given that stroma VASH1 expression level is a significant prognostic factor in colon cancer development, we also retrospectively analyzed the correlations of VASH1 expression levels in cancer cells with the clinicopathological factors of colon cancer patients." (PMID 25797264, 2015). "These in vitro studies provided us important information regarding the importance of VASH1 in controlling colon cancer tumor cell growth and metastasis." (PMID 25797264, 2015). "Mechanistic studies using suitable animal models are needed to firmly establish the role of VASH1 in human colon cancer development." (PMID 25797264, 2015). "Our studies demonstrated that stroma VASH1 expression levels were strongly negatively correlated with tumor size, advanced clinical stage, and other organ metastases in colon cancer patients." (PMID 25797264, 2015). "Our results collectively suggested that overexpression of VASH1 in colon cancer cells can induce both cell apoptosis and senescence, resulting in the inhibition of cancer cell growth and colony formation." (PMID 25797264, 2015). "As expected, VASH1 expression was detected in the cytoplasm of colon cancer cells with varied expression densities." (PMID 25797264, 2015). "Based on the clinical sample analyses, we demonstrated that colon cancer stroma VASH1 is critical for cancer angiogenesis and its levels are strongly negatively correlated with tumor size, advanced clinical stage, and other organ metastases." (PMID 25797264, 2015). "Our results collectively suggest that both active angiogenesis and lymphoangiogenesis exist in colon cancer patients, and that VASH1 is prevalent in the cancer stroma of cancer tissues." (PMID 25797264, 2015). "In the current study, we retrospectively analyzed the correlations of stroma VASH1 expression levels with the cancer clinicopathological factors of colon cancer patients." (PMID 25797264, 2015). "Human colon cancer HCT116 cells transfected with VASH1-specific or control shRNA were injected tail intravenously into Rag1−/− mice." (PMID 25797264, 2015). "Human colon cancer HCT116 cells transfected with VASH1 shRNA or control shRNA, were subcutaneously injected into Rag1−/− mice." (PMID 25797264, 2015).
colon cancer (continued). "Overexpression of VASH1 in colon cancer cells induced apoptosis and senescence, inhibiting cancer cell growth and colony formation in vitro and tumor growth in vivo." (PMID 25797264, 2015). "These novel findings prompted us to investigate the functional role of VASH1 in the pathogenesis of human colon cancer." (PMID 25797264, 2015). "Taken together, our studies identify that VASH1 functions as a significant tumor suppressor in human colon cancer that not only can inhibit cancer angiogenesis but also direct control cancer cell fate and biological functions." (PMID 25797264, 2015). "VASH1 expression has been found in cancer cells including in colon cancer, but the mechanisms responsible for the regulation of cancer cell growth and biological characteristics or functions are unclear." (PMID 25797264, 2015). "The median numbers of VASH1+ vessels in cancer stroma of colon cancer samples was used as a cutoff point to define the VASH1-high and VASH1-low groups." (PMID 25797264, 2015). "Our current studies have identified that VASH1 functions as a significant tumor suppressor in human colon cancer." (PMID 25797264, 2015). "In our current studies, we observed that VASH1 endogenously expressed both in primary cancer cells from colon cancer patients as well as in colon cancer cell lines." (PMID 25797264, 2015). "In addition, low VASH1 levels are correlated with large tumor size, advanced clinical staging, and distant metastasis in colon cancer patients." (PMID 38281945, 2024). "Thus, we show that Q3G has antitumor activity, impairs vascularization, and differentially modulates VASH1 and 2 expressions in colon cancer." (PMID 35145607, 2022). "According to studies, in colon cancer, VASH1 is mainly expressed in tumor cells and endothelial cells, and the function of VASH1 is different, and VASH1 overexpression in tumor cells can significantly inhibit the proliferation, migration, and cloning ability of tumor cells." (PMID 36504559, 2022). "Our studies indicate that VASH1 could be not only a useful prognosis biomarker but also a novel therapeutic target for human colon cancer." (PMID 25797264, 2015). "Stroma VASH1 expression levels (numbers of VASH1+ vessels) were strongly negatively correlated with tumor size (p=0.02), advanced clinical stage (p=0.006), and increased other organ metastases (p=0.003) in colon cancer patients." (PMID 25797264, 2015). "However, the VASH2 expression patterns in colon cancer cell lines are different from that of VASH1 expression." (PMID 25797264, 2015). "Therefore, our future efforts should expand the colon cancer sample size to further confirm the functional role of VASH1 in the angiogenesis regulation and pathogenesis of colon cancer." (PMID 25797264, 2015). "We also performed a parallel xenograft model to investigate whether knockdown of VASH1 in colon cancer cells can promote tumor growth and tumorigenesis." (PMID 25797264, 2015). "Furthermore, we also analyzed the VASH1 expression in colon cancer cells and determined its regulations on cancer cell fate and biological functions." (PMID 25797264, 2015). "We next performed complementary in vivo studies, using human colon cancer cells in humanized nude and Rag1−/− immunodeficient mouse models, and explored whether VASH1 is critical for the tumorigenesis and metastasis of colon cancer in vivo." (PMID 25797264, 2015). "Finally, VASH1 expression can control tumorigenesis and metastasis in vivo in human colon cancer models." (PMID 25797264, 2015). "We first performed xenograft models to investigate whether overexpression of VASH1 in colon cancer cells can inhibit tumor growth and tumorigenesis." (PMID 25797264, 2015). "We also confirmed that prevalent expression of VASH1 in endothelial cells in colon cancer stroma and paracancerous normal tissues, further suggesting the dynamic balance and regulation between angiogenic and antiangiogenic actions within the colon cancer tumor microenvironment." (PMID 25797264, 2015).
colon cancer (continued). "Given that our studies showed VASH1 expression in both primary colon cancer cells and cancer cell lines, and that its intratumoral expression levels were associated with tumor metastases, we reasoned that VASH1 may directly influence cancer cell growth and metastasis capacity." (PMID 25797264, 2015). "We thus determined whether VASH1 is also expressed in colon cancer cells." (PMID 25797264, 2015). "However, the clinical relevance of VASH1 in colon cancer and its regulations on cancer angiogenesis and cancer cell biological characteristics are still unknown." (PMID 25797264, 2015). "However, in the paracancerous normal tissues, the numbers of VASH1+ vessels are very low (mean numbers of 3.1), whereas significantly increased numbers of VASH1 expression in vascular endothelial cells were detected in colon cancer stroma (mean numbers of 4.7)." (PMID 25797264, 2015). "Furthermore, it remains unclear how VASH1 performs antiangiogenic actions in colon cancer in vivo." (PMID 25797264, 2015). "However, we didn't find correlations between stroma VASH1 expression levels with clinical outcomes of RFS and OS in colon cancer patients." (PMID 25797264, 2015). "Interestingly, we didn't observed a correlation between the cancer stroma VASH1 expression and cancer cell VEGF-A in colon cancer patients." (PMID 25797264, 2015). "Furthermore, box plot and linear correlation analyses demonstrated that there was a significant correlation between stroma VASH1 and CD34, a key microvessel density (MVD) marker, in colon cancer tissues." (PMID 25797264, 2015). "Taken together, these data suggest that VASH1 is a critical antiangiogenic molecule rather than a marker for lymphoangiogenesis in colon cancer patients." (PMID 25797264, 2015). "To further investigate the functional effect and correlation of VASH1 and CD34 involved in the active angiogenesis in colon cancer, we determined whether VASH1 expression was co-localized with CD34 in endothelial cells in cancer stroma." (PMID 25797264, 2015). "However, significant correlation and co-expression between stromal VASH1 and microvessel density marker CD34 were found in colon cancer tissues." (PMID 25797264, 2015). "In addition, serial tissue sections with immunohistochemical staining analyses further confirmed that VASH1 and CD34 molecules were co-expressed in blood endothelial cells in colon cancer tissues." (PMID 25797264, 2015). "Among the three colon cancer cell lines, HT29 cell line is with lowest expression levels for both VASH1A and VASH1-B, while HCT116 cell line is with the highest expression for both of the VASH1 isoforms." (PMID 25797264, 2015). "Interestingly, our results are different from recent reports showing that VASH1 expression has significant positive correlation with pathological TNM stage, tumor stromal invasion, lymph node status and distant metastasis, and negative correlation with OS and RFS in colon cancer." (PMID 25797264, 2015).
hepatocellular carcinoma (6 papers, 2015 to 2024). A malignant tumor that arises from hepatocytes. "CAFs have been reported to promote angiogenesis via VEGF secretion in hepatocellular carcinoma, which is associated with up-regulation of enhancer of zeste homolog 2 (EZH2) and further inhibition of vasohibin 1 (VASH1)." (PMID 32957712, 2020). "It has been reported that CAFs promote hepatocellular carcinoma angiogenesis and metastasis through VEGF-induced upregulation of EZH2 and subsequent downregulation of vasohibin 1, a negative regulator of angiogenesis, emphasizing an important role of EZH2 in mediating the function of CAFs." (PMID 36038549, 2022).